STAT3 (signal transducer and activator of transcription 3)
Diseases named in the same sentence as STAT3 in open-access papers (continued):
Sharing a sentence is not in itself a finding about the gene and the disease.
tumor (continued). "Further studies showed that both drugs were able to cause TNBC cell growth arrest and apoptosis in vitro and suppress TNBC tumor growth, angiogenesis, and metastasis in vivo by inhibiting STAT3." (PMID 31088482, 2019). "Napabucasin (BBI608), a novel small molecule inhibitor of STAT3, has been identified to eliminate stemness-like tumor cells in some cancers." (PMID 31277685, 2019). "The major limitation of this study lies in the comparatively low perfusion range of siRNA achieved, providing an explanation why reduction of Stat3 expression (and its target genes) in the bulk tumor can be considered only as minor." (PMID 30857197, 2019). "While STAT3 has been strongly implicated as a driver of oncogenesis, evidence suggests that persistent cytokine activation of STAT3 in pre-malignant lesions, engages a tumor suppressive senescence response." (PMID 31684144, 2019). "Constitutive activation of STAT3 has been reported in several tumor types and has been proved to be involved in proliferation, survival, inflammation, invasion, metastasis, and angiogenesis." (PMID 30691132, 2019). "Mechanistically, NEAT1 serves as a molecular sponge for miR-361, a pivotal tumor suppressor that suppresses proliferation, invasion, sphere formation and TX resistance by directly targeting the oncogene STAT3." (PMID 31287002, 2019). "STAT3 and STAT5 are transcription factors implicated in various tumor cell proliferation, migration, and invasion." (PMID 31783691, 2019). "This, along with the role of SOCS3 in promoting insensitivity of malignant cells to cytokine signaling, demonstrates how STAT3 overexpression can shape the tumor microenvironment." (PMID 31684088, 2019). "Tumor tissue also expressed high levels of the histone deacetylase HDAC5 and the SUMO/ubiquitin E3 ligase TRIM28, which is linked to STAT3 signaling, as well as low expression of the tumor suppressor PTGIS." (PMID 30645971, 2019). "The combination of AKT and STAT3 inhibitors significantly increases the anti-tumor effect compared to single-agent treatments." (PMID 30755611, 2019). "Mechanistically, we found that dynasore exerted anti-tumor effects, or at least anti-proliferation effect, in OS via STAT3 signaling pathway." (PMID 31534119, 2019). "This in turn leads to an increase in tumor cell invasion and metastasis via phosphorylation of STAT3, which in turn promotes the transcription of matrix metallopeptidase 9 (MMP9) by binding to the MMP9 promoter." (PMID 31555295, 2019). "In conclusion, HSP27 plays a very important role in STAT3/5 signaling, both in contexts of tumor development and others such as placenta development." (PMID 31861612, 2019). "Tumour cell-secreted IL-6 and IL-8 impair the activity and function of NK cells via STAT3 signalling and contribute to oesophageal squamous cell carcinoma malignancy." (PMID 31324197, 2019). "In turn, this activates STAT3, thus forming autocrine and paracrine feed-forward loops that promote tumor inflammation." (PMID 30781521, 2019). "Compelling evidence has demonstrated the crucial role of STAT3 in promoting tumor cell proliferation, angiogenesis, metastasis and resistance to therapies by regulating the expression of correlative genes such as vascular endothelial growth factor (VEGF)." (PMID 31287013, 2019). "STAT3 activation promote basal-type UBC progression by affecting tumor cell viability, proliferation and stromal invasion." (PMID 31438567, 2019). "In the present review, we describe the various ongoing efforts for delivery of anti-tumor drugs primarily targeting oncogenic STAT3 signaling pathway." (PMID 31569687, 2019). "The aberrant expression of STAT3 and STAT5 in the TME is chiefly associated with tumor progression and spread." (PMID 31842362, 2019). "In NKTCL tumor cell lines with constitutive STAT3 phosphorylation and high levels of PD-L1 expression, treatment with Stattic and a STAT3 specific antisense oligonucleotide led to decreased pSTAT3 and PD-L1 expression." (PMID 31684088, 2019).
tumor (continued). "Several studies have described that GPRC5A plays a role in tumor initiation by affecting the signal transducer and activator of the transcription 3 (STAT3) signaling pathway." (PMID 31246342, 2019). "Previous research findings indicated that combined targeting of IL-6/JAK/STAT pathway and PD-L1 resulted in restricted tumor growth in in vivo models, while in others, STAT3 targeting increased the efficacy of anti-PD1 mAb." (PMID 31581535, 2019). "In breast cancer, nobiletin has been found to significantly inhibit the protein tyrosine kinase 2 (PTK2)/SRC/STAT3 angiogenetic signaling pathway, and, consequently, tumor proliferation." (PMID 31354472, 2019). "This interaction can lead to the inactivation of STAT3 and subsequently, sensitize tumor cells into apoptotic cell death." (PMID 31569687, 2019). "In one of the early studies, simultaneous shRNA-mediated knockdown of PTEN and deletion of STAT3 showed substantial increase in in vitro proliferation cells and tumor formation in SCID (Severe combined immunodeficient) mice in astrocytes." (PMID 31847229, 2019). "The binding of STAT3 to a specific DNA domain promotes the expression of numerous genes involved in cell cycle progression, apoptosis, tumor angiogenesis, invasion, metastasis, chemoresistance, immunosuppression, and cancer stem cell renewal." (PMID 31781335, 2019). "Survivin, Mcl-1, and VEGF are examples of tumor-related factors whose expressions are thought to be regulated by STAT3." (PMID 30755233, 2019). "The identification of the specific signaling pathway activated by CXCR2 provides a novel regulatory mechanism of STAT3 activation in myeloid cell differentiation and a potential strategy for reducing immune suppression in the tumor microenvironment." (PMID 31395859, 2019). "Further analysis showed that there was a positive correlation between STAT3 mRNA and hsa-mir-21-5p in both tumor tissues and adjacent normal tissues (r = 0.75, 0.78)." (PMID 31270251, 2019). "There was a significant increase in the two kind of T cell populations among PBMCs co-cultured with STAT3 sh tumor cells in combination with anti-PD-L1." (PMID 31511071, 2019). "Interleukin-6 (IL-6) is the most important STAT3 activator and promotes tumor cell proliferation, survival, invasion, angiogenesis." (PMID 30606233, 2019). "STAT3 inhibits the expression of mediators activating immune response against tumor cells and has pro-mitogenic and anti-apoptotic effects on tumor cells." (PMID 30700007, 2019). "They act in oncogenic signaling pathways, such as NF-κB and STAT3, which enhance tumor survival and proliferation." (PMID 31010101, 2019). "IL-6, for example, is responsible for promoting colon tumourigenesis by inducing the production of STAT3-mediated IL-10 in tumour cells." (PMID 30931335, 2019). "The studies suggesting the importance of STAT3 as a marker of tumor progression and aggressiveness are based on GC samples derived from an Asian population, while the ones used in this study are from Caucasian (European) patients." (PMID 31234597, 2019). "Among the most prominent proteins overexpressed in tumor tissue we identified the oncogenic transcription factor STAT3." (PMID 30645971, 2019). "Another study showed that the expression of STAT3 was significantly reduced in cells treated with HO-3867 and combination treatment severely reduced cell growth in a platinum-resistant tumor xenograft model as compared to treatment with cisplatin alone." (PMID 31766284, 2019). "For instance, STAT1 can enhance IFN-γ production and the cytotoxicity of NK cells; phosphorylated STAT3 can impair tumour immune surveillance and promote tumour escape from immune control." (PMID 31324197, 2019). "Mechanistically, PIPKIγ facilitated PI3K-Akt-mTOR signaling pathway activation to increase STAT3 phosphorylation levels, thus triggering CCL2 transcription to enhance tumor-associated macrophage recruitment." (PMID 31781676, 2019).
tumor (continued). "STAT3 pathway facilitates crosstalk between tumor cells and endothelial cells that mediates pro-angiogenic signaling." (PMID 31861720, 2019). "Alterations in the profile of cysteine cathepsins in cancer re-shape immunity in such a way as to foster tumor progression and STAT-3 appears to mediate the crosstalk between cancer cells and the immune system." (PMID 31555270, 2019). "Decreased phospho-Stat3 levels were also confirmed in western blot analyses of whole tumor lysates, while Stat3 protein levels remained stable." (PMID 30857197, 2019). "Where environmental-STAT3 seemed to play a dominant role at primary pancreatic sites, tumor-specific STAT3 seemed dominant at metastatic sites where its high activity persisted." (PMID 31796877, 2019). "Various STAT3-dependent pro-tumor functions have been proposed for UBC, including the expansion of cancer stem cells." (PMID 31438567, 2019). "Upon IL-4 stimulation, 4/21 ICR activated the STAT3 pathway and promoted Th17-like polarization and tumor-targeted cytotoxicity in CAR-T cells in vitro." (PMID 31379876, 2019). "Previous studies have shown that STAT3 plays a vital role in preventing cell apoptosis and stimulating cell proliferation during tumor development." (PMID 30914735, 2019). "Further, the investigation of Priego and colleagues highlights the particular role of STAT3 labeled reactive astrocytes in the tumor environment of brain metastasis." (PMID 31186414, 2019). "Here, we present levels of phosphorylated STAT3 (Tyr705) and total STAT3 protein in LV tissue of tumour-free (control) and B16F10 bearing WT and CKO mice." (PMID 31667271, 2019). "We observed elevated levels of Jak and Stat3 mRNA in the tumor control group, which were significantly reduced in the 10 mg/kg ajoene extract-treated mice (Jak, p = 0.029; Stat3, p = 0.046)." (PMID 31717643, 2019). "In tumor cells, constitutive activation of STAT3 inhibits anti-tumor immune response by blocking the secretion of proinflammatory cytokines and suppressing dendritic cell function." (PMID 31684858, 2019). "This experimental design displays the clear mechanism of gigantol treatment in attenuation of the CSC-supportive PI3K/AKT/mTOR and JAK/STAT3 signals at the time of tumor initiation." (PMID 31861050, 2019). "Unexpectedly, STAT3 has recently been demonstrated to have a tumor-suppressive role in KRASG12D-induced lung tumorigenesis." (PMID 31296870, 2019). "STAT3 signaling contributes as well to a dynamic crosstalk between tumor cells and immune cells, including macrophages, CD8+ T-cells, myeloid-derived suppressor cells, T-regs and NK cells." (PMID 31581535, 2019). "Enhanced STAT3 activation by tRXRα was confirmed by immunohistochemical staining in tumor tissues from Tg-tRXRα and control mice treated with AOM/DSS or DSS." (PMID 30931933, 2019). "Upregulation of Bv8 following STAT3 activation is responsible for neutrophil-mediated tumor angiogenesis in the early stages of Rip-Tag pancreatic insulinoma." (PMID 31474975, 2019). "Stattic is a tool for inhibiting STAT3 in animal tumor models displaying constitutive STAT3 activation." (PMID 31485245, 2019). "As SC-induced growth suppression was reversed by overexpression of constitutively active STAT3 (where Tyr705 was replaced by an aspartate residue), we conclude that SC anti-tumor effect was phospho-705-STAT3 dependent." (PMID 31422383, 2019). "Several studies demonstrated a link between STAT3 blockade, TGFβ inhibition and increased tumor surveillance by NK cells." (PMID 31057536, 2019). "Several lines of evidence suggests that inhibition of STAT3 triggers activation of dendritic cells, T cells, natural killer cells, enhancing tumor immune suppression, therefore, inhibiting tumor growth and metastasis." (PMID 31534498, 2019).
tumor (continued). "IL-27p28, the ligand for IL27RA, has been linked with tumor progression, self-renewal and tumorigenicity, expression of inflammatory mediators, tumor immune invasion and regulated chemokine axis via STAT1/STAT3 signaling." (PMID 31628349, 2019). "Our data suggest that the LPP PEIs only reach a sub-fraction of the tumor cells, as seen by a clear tendency towards reduced Stat3-mRNA expression in the tumor core region." (PMID 30857197, 2019). "Consistent with in vitro findings, bazedoxifene alone also attenuated HCT-15 xenograft tumor burden and reduced p-STAT3, p-AKT and p-ERK in vivo." (PMID 30736824, 2019). "In activated B cell subtype of diffuse large B cell lymphomas (DLBCL-ABC), in vivo inhibition of STAT3 was found to be a more effective strategy in suppressing tumour growth than targeting upstream JAK inhibition." (PMID 30876435, 2019). "There is strong evidence that STAT3 is a key signaling molecule involved in tumor progression and STAT3 activation affects proliferation, growth, and apoptosis." (PMID 31361777, 2019). "This motivated us to further distinguish the regulatory activity of STAT3 in the tumor and TME compartment." (PMID 31796877, 2019). "STAT3 is a key mediator of molecular mechanisms that drive tumor progression and promote immune escape." (PMID 31511071, 2019). "Collectively, our results indicate that genetic manipulation of STAT3 promotes anti-tumor immunity by enhancing the proportion of T cells and their capacity to kill tumor cells." (PMID 31511071, 2019). "CCT also binds to signal transducer and activator of transcription 3 (Stat3), which is an oncogenic transcription factor contributing to tumor formation and malignancies, via the CCTγ subunit in an ATP-dependent manner." (PMID 30506376, 2019). "Oncogene-induced STAT3-activation is central to tumor progression by promoting cancer cell expression of pro-angiogenic and immunosuppressive factors." (PMID 31766350, 2019). "Cytokine IL-6, which has a dual role in the anti-tumor immunity, activates signaling proteins Stat1 and Stat3 in addition to its other functions." (PMID 31709183, 2019). "Effects of STAT3 KO on cell proliferation, migration and spheroid formation were assessed in vitro and effects on in vivo tumor growth were tested using several tumor xenograft models." (PMID 31534498, 2019). "STAT3 is required for NPM-ALK mediated lymphomagenesis in mouse embryonic fibroblasts, and loss of STAT3 led to increased apoptosis and decreased tumor formation." (PMID 31684088, 2019). "Previous studies also suggest that the inhibition of STAT3 signaling can regulate apoptosis in tumor cells." (PMID 31575007, 2019). "In tumor-infiltrating Tregs, both STAT3 and STAT5 bind to a STAT consensus site in the Foxp3 promoter to enhance FOXP3 expression which seems to be important in maintaining Tregs inhibitory functions." (PMID 31480382, 2019). "In tumor samples, 18 out of 24 ALK− ALCL samples had PD-L1 expression, compared to 18 out of 36 ALK+ ALCL tumor samples, and in both groups PD-L1 expression was correlated with STAT3 activation." (PMID 31684088, 2019). "Tumor-derived exosomes induce proliferation and expression of STAT3 in myeloid-derived suppressor cells (MDSCs) through Hsp72." (PMID 30925917, 2019). "As such, STAT3 promotes an immunosuppressive tumor microenvironment, which can be partly attributed to reduced NK cell activity." (PMID 31658669, 2019). "STAT3 has been reported to be involved in oncogenesis by up-regulating the transcription of several genes that control primary tumor cell survival, resistance to apoptosis, cell cycle activation, and angiogenesis." (PMID 32257917, 2019). "In line with unchanged Stat3 activation in tumor epithelia, tumor sizes and proliferation rates determined by BrdU incorporation were comparable to control mice." (PMID 30353167, 2019).
tumor (continued). "Cryptotanshinone, another SHP2 inhibitor extracted from natural plants, has also been reported to show tumor-suppressive effects upon GBM cells via suppression of STAT3 activation." (PMID 30791455, 2019). "While STAT2 and STAT4 promote the anti-tumor immune response, STAT3 and STAT6 mediate immunosuppression in the TME, and STAT1 and STAT5 have been implicated in both activation and suppression of the anti-tumor immune response." (PMID 31057536, 2019). "Altogether, these studies suggest that a general inhibition of STAT3 in T cells would be a beneficial treatment for increasing tumor control." (PMID 31766350, 2019). "Tumor spheroids isolated from the ascites of recurrent EOC patients are enriched with tumor cells overexpressing STAT3 compared with cells isolated from the ascites of chemotherapy-naïve patients." (PMID 31861720, 2019). "In our study that YPFS inhibit the angiogenesis by decreasing the expression of TSLP/STAT3, which is in accordance with the improvement of immunosuppression of the tumor microenvironment." (PMID 31885639, 2019). "The proposed mechanism involves inhibition of STAT3 activation, and such inhibition by the tyrosine kinase inhibitor sunitinib in tumor-bearing mice also reduces MDSC numbers." (PMID 31417568, 2019). "In some human tumor models, dovitinib was shown to inhibit the STAT3/5, MAPK, PI3K/AKT/mTOR, and Wnt signaling pathways." (PMID 31485222, 2019). "Inhibition of JAK2/STAT3 activation can trigger cell apoptosis in vitro and inhibit tumor growth in an HL xenograft mouse model." (PMID 31861597, 2019). "NF-κB is necessary to promote the survival and proliferation of cancer cells by inducing the expression of anti-apoptotic genes (BCL-2) and activating cyclin, and activation of STAT3 in tumor cells enhances the ability of tumors to escape the immune system." (PMID 31134006, 2019). "Tumor-infiltrating T-cells exist as distinct populations, and here we highlight a few main types of T-cell players that are regulated through STAT3/5 signaling." (PMID 31861720, 2019). "In multiple cell types, increasing evidence has demonstrated that STAT3 functions as a tumor oncogene." (PMID 31486564, 2019). "The crucial role of STAT3 in tumor cell survival, proliferation, migration, invasion, and metastasis is well established and, thus, it is targeting for therapy assaults cancer on multiple fronts." (PMID 31695609, 2019). "Specifically, we defined tumor- and environmental-specific STAT3 target genes identified from ChIP-seq experiments, and then calculated compartment-specific STAT3 activities based on the relative expression levels of its target genes." (PMID 31796877, 2019). "Signal transducer and activator of transcription 3 (STAT3) plays a critical role in tumor development and mediates many cellular processes such as proliferation and apoptosis." (PMID 31777595, 2019). "Current scientific evidence indicates that persistently activated STAT3 plays an important role in tumor onset and progression via mechanisms involving proliferation, invasion, and migration." (PMID 30863721, 2019). "Cantharidin and its analogues have shown strong anticancer effects, including STAT3 inhibition, in several tumor cells." (PMID 31422383, 2019). "Hyperactivation of STAT3 in myeloid cells simultaneously exerted anti-inflammatory as well as anti-tumor effects." (PMID 31480382, 2019). "Pharmacological blockade of ERBB or STAT3 prevented tumor growth in xenograft models and restored MHC class I expression." (PMID 30645971, 2019). "Gene Set Enrichment Analysis (GSEA) of STAT3 target genes showed that tumor-specific genes were enriched in DNA replication and RNA transcription, showing enrichment in for example “packaging of telomers”, “meiotic synapsis” and “RNA pol I promoter opening”." (PMID 31796877, 2019). "We further demonstrated that lincRNA-p21 acts as a tumor suppressor via direct binding to STAT3 and inhibition of its transcriptional activation." (PMID 30857539, 2019).